TMEM102 (transmembrane protein 102)
Description:
Selectively involved in CSF2 deprivation-induced apoptosis via a mitochondria-dependent pathway.
Synonyms: CBAP; FLJ36878; D2B
Tractability: Antibody: UniProt places it where antibodies can reach, with high confidence; UniProt predicts a signal peptide or a membrane-spanning region; its Gene Ontology location is reachable by antibodies, with medium confidence. PROTAC: ubiquitination databases record sites on it; its protein half-life has been measured.
Gene: Protein-coding gene on chromosome 17 (7,435,430 to 7,437,679, forward strand). Ensembl gene ENSG00000181284.
Subcellular location: Cell membrane
Subcellular location (Human Protein Atlas): Vesicles
Gene Ontology:
Molecular function: protein binding
Biological process: positive regulation of cell adhesion; positive regulation of T cell migration; regulation of mitochondrial outer membrane permeabilization involved in apoptotic signaling pathway; response to cytokine; signal transduction
Cellular component: cell surface; protein-containing complex; plasma membrane
Genetic constraint (gnomAD): Loss-of-function variants: 30 observed, 25.84 expected, observed/expected ratio (o/e) 1.16, 90% interval 0.87 to 1.57. The upper end of that interval is the gene's LOEUF score, 1.57, which puts it in group 6 of 6, group 1 being the genes least tolerant of losing a copy. Missense variants: 677 observed, 664.4 expected, observed/expected ratio (o/e) 1.02, 90% interval 0.96 to 1.09. Synonymous variants: 306 observed, 313.16 expected, observed/expected ratio (o/e) 0.98, 90% interval 0.89 to 1.07.
Homologues: Orthologues: chimpanzee TMEM102 (99% identical), macaque TMEM102 (97% identical), dog TMEM102 (85% identical), rabbit TMEM102 (85% identical), guinea pig TMEM102 (84% identical), pig TMEM102 (83% identical), mouse Tmem102 (80% identical), rat Tmem102 (77% identical), zebrafish tmem102 (31% identical), Drosophila melanogaster CG15865 (20% identical). Paralogues in human: MB21D2 (29% identical), ITPRIPL2 (15% identical), ITPRIP (12% identical), ITPRIPL1 (10% identical), MAB21L3 (10% identical), CGAS (9% identical), MAB21L4 (8% identical), MAB21L1 (8% identical), MAB21L2 (7% identical).
Diseases named in the same sentence as TMEM102 in open-access papers:
TMEM102 is named in the same sentence as 15 diseases in open-access papers, as found by Europe PMC text mining. Sharing a sentence is not in itself a finding about the gene and the disease. The quoted sentences say what the papers report.
hyperreactivity (1 paper, 2023). "TRPM4 is associated with cold airway hyperreactivity, TMEM102 and CD200R1 are involved in Th cell activation, and ST3GAL3 and B3GNT7 are associated with protecting the distal airways against destruction." (PMID 38203236, 2023).
TMEM102 also shares sentences with these, for which no sentence is quoted: tumor (8 papers); prostate carcinoma (4); acute lymphoblastic leukemia (1); acute myeloid leukemia (1); anemia (1); Autoimmunity (1); cancer (1); diabetes mellitus (1); Hypertension (1); Immunodeficiency (1); leukemia (1); metabolic disease (1); T-cell acute lymphoblastic leukemia (1); T-cell leukemia (1).